MMP9 (matrix metallopeptidase 9)
Diseases named in the same sentence as MMP9 in open-access papers (continued):
Sharing a sentence is not in itself a finding about the gene and the disease.
Hypertension (continued). "Similarly, in a cohort of asymptomatic hypertensive patients, rs3918242 is associated with higher plasma MMP-9 and evidence of increased hypertension and vascular stiffness, measured by pulse wave velocity." (PMID 33579197, 2021). "The occurrence of hypertensive disorder complicating pregnancy can be caused by the decrease of the expression of MMP9 in the network, and AKT1, ESR1, FOS, VEGFA and other proteins play an important role in the pathogenesis of hypertensive disorder complicating pregnancy, such as preeclampsia." (PMID 34062719, 2021). "It was determined that MMP‐9 levels correlated linearly with PWV, suggesting that MMP‐9 may be, at least in part, a cause of arterial stiffening and hypertension." (PMID 29595876, 2018). "Moreover, MMP9 levels were affected by age and hypertension, and were positively associated with circulating CRP and Hcy." (PMID 30373522, 2018). "In the younger male group (<65 y/o), we found that TIMP1 rs4898 minor allele was associated with hypertension risk (OR = 2.16, 95% CI 1.24 to 3.76, P = 0.006) and MMP9 rs3787268 minor allele had a borderline protection from DM risk (OR = 0.5, 95% CI 0.26 to 0.98, P = 0.04)." (PMID 25932641, 2015). "It is now believed that HCRP and MMP9 represent the underlying mechanisms leading to the formation of human atheroma, favouring both the destabilization of vulnerable plaques and the formation of occlusive thrombus especially in patients with hypertension." (PMID 23606891, 2013). "Cardiac fibrosis is a deleterious consequence of hypertension which may further advance to heart failure and increased matrix metalloproteinase-9 (MMP-9) contributes to the underlying mechanism." (PMID 23533637, 2013). "Elevated circulating levels of MMP-9 may play a role in the development of hypertension and increased risk of death by CVD." (PMID 21698093, 2011). "MMP-9 activation is triggered under stress conditions including inflammation and oxidative stress and is consequently upregulated in inflammation-dependent conditions such as hypertension and associated with cardiovascular risk in patients undergoing hemodialysis." (PMID 32225016, 2020). "Interestingly, an elevated MMP-9 secretion was reported to be induced by hypoxia conditions, which triggered us to investigate whether and how serum MMP-9 in OSAS patients affects the risk of systematic hypertension and heart dysfunction." (PMID 29693002, 2018). "This supports the hypothesis that, in patients at risk for cardiovascular disease such as hypertension, peripheral endothelial dysfunction extends to the bone marrow and may result in reduced NO bioavailability and, consequently, impaired MMP9-dependent (E)PC mobilization." (PMID 23554866, 2013). "Conversely, immunohistochemistry measurements of fibrosis indicators MMP2 and MMP9 in the PBS group showed significantly more expression compared to the control level due to the stimulation of hypertension." (PMID 41551933, 2026). "In hypertension, MMP-9 is also upregulated, contributing to the development of vascular inflammation and oxidative stress." (PMID 40492135, 2025). "Area of perivascular MMP9 was 2.8 fold larger in the periventricular WMH compared to NAWM in individuals with hypertension and control individuals (p < 0.001)." (PMID 40219923, 2025). "Resveratrol, a polyphenol found in grapes and berries, has been shown to inhibit MMP-2 and MMP-9 activity, reduce oxidative stress, and improve vascular function in animal models of hypertension." (PMID 40492135, 2025). "It has been demonstrated that MMP-2 and MMP-9 specifically contribute to the development of hypertension by cleaving extracellular matrix proteins, which results in vascular stiffness and elevated blood pressure." (PMID 40492135, 2025).
Hypertension (continued). "A related investigation indicates that the deletion of MMP9 in hypertensive rat models reinstates the autoregulation of renal blood flow and mitigates the progression of hypertension, proteinuria, glomerular damage, and renal interstitial fibrosis." (PMID 40492135, 2025). "Curcumin has been shown to inhibit MMP-2 and MMP-9 activity, reduce inflammation, and improve endothelial function in animal models of hypertension." (PMID 40492135, 2025). "Studies have shown that the knocking out of matrix metalloproteinase 9 (MMP9) in hypertensive rats can prevent the development of hypertension, proteinuria, glomerular damage, and renal interstitial fibrosis." (PMID 39272451, 2024). "PPI network analysis revealed three potential key targets—MMP9, HIF1A, and BCL2—that are significantly implicated in the treatment of hypertension with catechins." (PMID 39272451, 2024). "Increased expression or activity of MMP-2 and/or MMP-9 proteins has been most frequently observed in dysglycemia, hypertension, oxidized LDL and high LDL levels, and inflammation." (PMID 39596317, 2024). "CG, GCG, ECG, and EGCG were identified as key catechin components for combating hypertension, with MMP9, HIF1A, and BCL2 as potential critical therapeutic targets." (PMID 39272451, 2024). "This makes this combination particularlyuseful in hypertension and related cardiovascular disorders where suppression of MMP-9 and TIMP-1 activities decreases the relatedcomplications and improves the overall morbidity and mortality." (PMID 37886137, 2023). "Other studies revealed matrix metalloproteinase-9 (MMP-9) is a useful marker in identifying hypertension in patients with sleep apnoea." (PMID 36792325, 2023). "In human studies and clinical trials, in patients with arterial hypertension significantly higher serum levels of MMP-9 but a decrease in the results of hypertensive treatment were reported." (PMID 36835040, 2023). "CUR treatment prevented morphological alterations in the aorta wall found in 2K-1C hypertensive rats and significantly reduced matrix metalloproteinase-2 (MMP-2) and matrix metalloproteinase-9 (MMP-9) levels in the aortic walls generated by 2K-1C hypertension." (PMID 36770715, 2023). "From this point it is significant that aging is associated with increasing ApoE levels, it leads to increased NF-kB activity in cerebral vessels, and aging and hypertension interact to promote increased MMP-9 activity and formation of cerebral microbleeds." (PMID 38073626, 2023). "More importantly, increased MMP2 and MMP9 were found to increase the risks of cardiovascular disease and clinical hypertension in children with obesity." (PMID 36034923, 2022). "Our summary theory, based on an extensive review of over 102 published studies in this field, is that high blood pressure activates MMP-2, where MMP-2 has been shown to activate pro-MMP-9, and MMP-9 has been reported to increase the risk of hypertension." (PMID 35742125, 2022). "In obese people with concomitant hypertension, higher levels of MMP-9 were found compared to obese normotensive patients." (PMID 36362386, 2022). "Regarding this, the activation of MMP-2 and MMP-9 was directly involved in the vascular remodeling observed in hypertension." (PMID 35625532, 2022). "Different ventricular remodeling processes in hypertension are accompanied by variations in myocardial MMP-9 levels." (PMID 36193497, 2022). "The expressions of MMP-2 and MMP-9, which are involved in the development of hypertension, were significantly decreased in aortas from CP and MS rats." (PMID 35774422, 2022). "There was also a significant increase in blood pressure after MMP-9 injection, and hypertension can also lead to ventricular remodeling." (PMID 36193497, 2022). "In the PPI network, we observed that IL-6, CCL2, IL-1β, MMP-2, and MMP-9 were the hub targets of GZD for improving hypertension." (PMID 33906674, 2021).
Hypertension (continued). "The results suggest that the upregulation of the expression of TGF‐β1, TNF‐α, MMP‐2, and MMP‐9 contributes to the development of hypertension, proteinuria, and glomerular and tubular injury in Dahl S rats." (PMID 33377622, 2021). "Captopril is one of angiotensin-converting enzyme inhibitors (ACEIs) usually used to relieve hypertension and can also downregulate the expression of MMP9 and reactive oxygen species (ROS)." (PMID 34457122, 2021). "A previous report studying pregnancy‐related hypertensive disorders using placental tissues showed that MMP9 expression was significantly reduced in a severe hypertensive group when compared to healthy patients." (PMID 33942999, 2021). "For MMP-9, its high serum levels are likely responsible for the cleavage of β2-adrenergic receptors on endothelial cells and indicate a faster progression of hypertension in humans." (PMID 33023122, 2020). "It is well known that the onset of hypertension is related to MMP-9 activation concurrent with a rise in vessel distensibility." (PMID 32244956, 2020). "Patients given imidapril had a lower MMP-9 activity than those given lisinopril, indicating that different hypertension drugs had different inhibitory effects on MMP-9 activity." (PMID 33082709, 2020). "Lacerda L, Faria AP, Fontana V, Moreno H, Sandrim V. Role of MMP-2 and MMP-9 in resistance to drug therapy in patients with resistant hypertension." (PMID 32267335, 2020). "Our subgroup analysis was carried out to see if independent CVD risk factors such as age, BMI and a history of hypertension exerted significant influence on the extent of change in the levels of MMP-8, MMP-9 and TIMP-4 during the 5-year follow-up period." (PMID 32451401, 2020). "The only independent explanatory variable for MMP-9 levels was uric acid (p-value = 0.002), as corroborated by studies that point to uric acid as an independent predictor for the development of hypertension." (PMID 32164582, 2020). "The activity of MMP-9 leads to the development of hypertension at an early stage, generating collagen degradation and arterial debilitation." (PMID 33419373, 2020). "Elevated levels of MMP-9 and TIMP-1 in patients with essential hypertension are associated with increased arterial stiffness." (PMID 33419373, 2020). "Previous studies have reported that apelin promotes collagen deposition and increases the expression of MMP-2 or MMP-9 in overnourished mice or rats with hypertension-induced left ventricular hypertrophy." (PMID 31829402, 2019). "(2013) confirms the finding that MMP‐9 levels are higher in individuals with hypertension and that antihypertensive treatment lowers MMP‐9 to control group levels." (PMID 29595876, 2018). "One of the most significant hypertension drug targets is β2AR, and there has been a study reported the possible role of β2AR as a MMP-9 substrate." (PMID 29693002, 2018). "An elevated MMP-9 serum level in OSAS patients indicates the unfavorable progression of hypertension and heart dysfunction." (PMID 29693002, 2018). "Compared to control group, AAA and TAA patients had increased MMP9 levels in either male or female, and this discrepancy was also found in hypertension status." (PMID 30373522, 2018). "Our study showed that a higher serum MMP-9 level in OSAS patients was correlated with hypertension and left ventricular hypertrophy occurrence." (PMID 29693002, 2018). "Increased TGF-β is related with increased collagen synthesis markers and is correlated with increased MMP-9 level in hypertensive disease patients." (PMID 30524357, 2018). "Later in pregnancy, an elevation in MMP-2 and MMP-9 induces abnormal release of vasoactive factors conditioning hypertension." (PMID 28726716, 2017). "Reasons for this conclusion, given our data from a previous study which showed that the concentrations of MMP-9 in patients with mild, and especially with severe, hypertension are reduced significantly, compared to those of controls." (PMID 27490532, 2016).
Hypertension (continued). "Further research is needed to investigate how glycemic control and antihypertensive drug therapy can affect concentrations of ET-1, MMP-2, MMP-9, and TIMPs, and what the relationship is of these molecules with the pathogenesis of hypertension in T2D." (PMID 27490532, 2016). "High abundance of MMP-9 has been observed in an animal model of hypertension and clinically in women with gestational hypertension." (PMID 26692905, 2015). "Of note, our results are in line with the literatures reporting that the circulating MMP-9 level is higher in patients with dyslipidemia, hypertension, hyperglycemia and central obesity." (PMID 26692905, 2015). "The serum concentration of MMP-9 is higher in subjects positively diagnosed with MetS and subjects with high blood pressure, elevated fasting blood glucose, low blood high-density lipoprotein-cholesterol (HDL-C), high blood triglycerides, and central obesity." (PMID 26692905, 2015). "Correlation between serum HCRP levels and MMP9 levels was analyzed using Spearman's correlations test in patients with hypertension." (PMID 23606891, 2013). "In conclusion, we show that renovascular fibrosis due to hypertension can be attributed in part, to increased expression and activity of MMP-9, -2, and -13." (PMID 24159376, 2013). "Hypertension stimulates MMP-9 secretion, and MMP-9 is one of the main candidates to induce cardiac remodeling." (PMID 23533637, 2013). "Significantly higher levels of MMP-9 have been reported in obese children with coexisting hypertension than in obese normotensive patients, and MMP-9 correlates with BMI." (PMID 23800102, 2013). "It was found that the positive rate of HCRP and MMP9 in hypertension complicated by vascular thrombosis event group is higher than that in the nonevent group." (PMID 23606891, 2013). "Most recently, MMP9 was found to promote hemorrhagic transformation and spontaneous intracerebral hemorrhage during hypertension." (PMID 21541054, 2011). "MMP-9 (gelatinase-B) functions in the degradation of type IV and V collagens, and its levels are raised in individuals with hypertension, acute coronary syndrome, and acute MI." (PMID 21887284, 2011). "This suggests that MMP-9 may play a protective role in the early stages of hypertension by preserving vascular compliance." (PMID 40492135, 2025). "Furthermore, intensity of perivascular MMP9 was 5% larger in WMH than in NAWM in individuals with hypertension and control individuals (p = 0.004)." (PMID 40219923, 2025). "Moreover, in models of cardiac arrest and lateral percussion-induced TBI, NaHS stabilizes the BBB by inhibiting MMP-9 and occludin, prevents vascular dysfunction, hypertension, and sympathetic hyperactivity, and restores CBS, CSE, and eNOS expression." (PMID 41465271, 2025). "Other studies have demonstrated that in obese subjects with metabolic syndrome and hypertension endothelial dysfunction may be predicted by the ratio between matrix metalloproteinase 9 (MMP-9) and tissue inhibitor of metalloproteinases (TIMPs)." (PMID 38474219, 2024). "Our study suggests that this may occur through a mechanism involving the induction of hypertension by oral axitinib, as well as MMP-9 degradation and the intravenous pembrolizumab destruction of elastin and collagen in the aortic wall." (PMID 38887778, 2024). "This combination could beuseful in hypertension and related cardiovascular disorders because suppression of MMP-9 and TIMP-1 activities will decrease thecomplications and improves the overall morbidity and mortality." (PMID 37886137, 2023). "Basic studies on hypertension have revealed that MMP-9 expression was significantly higher in conduct vessels with thicker intimas and media and the process could be blocked by MMP inhibitor (doxycycline) treatment." (PMID 37332754, 2023). "MMP9 acts at the level of the extracellular matrix in arterial hypertension, through collagen degradation consequent to vascular wall alteration and the development of hypertension." (PMID 37512106, 2023).
Hypertension (continued). "Alterations in specific MMPs, such as MMP-2 and MMP-9, which are gelatinases expressed on cell surfaces (MMP-2) or secreted (MMP-9) by endothelial cells and myofibroblasts influence arterial remodeling, leading to various pathological disorders that include hypertension." (PMID 35774422, 2022). "In turn, MMP-9 increased production in macprophages and smooth muscle cells was observed during dysglycemia or dyslipidemia, and its plasma concentration is elevated in cases of hypertension or obesity." (PMID 35769087, 2022). "Moreover, in hypertension, induced-MMP-9 at a very early stage enhances collagen breakdown and arterial destruction, with hypertensive patients presenting increased serum MMP-9 levels, which were related to aortic stiffness." (PMID 35628490, 2022). "MMP-2 and MMP-9 are also responsible for activating cytokines, such as transforming growth factor-β (TGF-β), which are involved in collagen accumulation and profibrotic alterations in remodeling that are associated with hypertension." (PMID 33923477, 2021). "Insufficient NOS/NO/MMP9 pathway resulted in impaired mobilization of EPCs in hypertension." (PMID 32455001, 2020). "In addition to the previously studied risk factors for unstable plaque formation such as hypertension, T2DM, and lipids, this study find that serum markers MMP-9, LOX-1, and YKL-40 are also independent risks of unstable plaque formation." (PMID 33003997, 2020). "The results showed that MMP‐2 and MMP‐9 levels in the pregnant hypertension rats were significantly reduced compared with those in the healthy pregnant rats, but such effects could be significantly rescued by TTR treatment (P < 0.05)." (PMID 32533762, 2020). "This could point to a more important role of MMP-2 in the development of hypertension in comparison with MMP-9 in this particular model." (PMID 33023122, 2020). "In human essential hypertension, plasma MMP-9 levels were higher than in normotensive patients." (PMID 33066113, 2020). "Attenuation of MMP-9 by chymase inhibition may contribute to the attenuation of vascular endothelial dysfunction in hypertension as well as to the prevention of vascular fragility." (PMID 33066113, 2020). "TIMP-1 is a major endogenous inhibitor of MMP-9 that may affect the responsiveness of hypertensive disorders of pregnancy to therapy." (PMID 33419373, 2020). "By multivariate analysis, hypertension was the sole predictive factor of MMP-9 elevation." (PMID 31878008, 2019). "Immunohistochemical experiments comparing preeclamptic women with age-matched controls based on placental sections of decidual cells and adjacent interstitial trophoblasts revealed that an elevated level of MMP9 is characteristic for gestation complicated by hypertension and proteinuria." (PMID 29670668, 2018). "This response is also related to the extracellular matrix degradation of elastic fibers since the up-regulation of matrix metalloproteinase-2 (MMP-2) and matrix metalloproteinase-9 (MMP-9) expression in vessel tissue has been confirmed in animal models of hypertension." (PMID 30347737, 2018). "Importantly, OSAS patients complicated with hypertension also exhibited elevated MMP-9 levels (P < 0.001), indicating the crosstalk between MMP-9 and hypertension." (PMID 29693002, 2018). "To determine whether MMP-9 can help predict the occurrence of cardiovascular diseases, we excluded the hypertension patients from our cohort (12/47) and followed up those without any cardiovascular dysfunction (n = 35) for up to five years." (PMID 29693002, 2018). "The lack of association between MMP-9 and cfPWV in the present study was in agreement with studies in patients with essential hypertension, coronary heart disease and bicuspid aortic valves." (PMID 29070037, 2017). "In keeping with this, we hypothesize that MMP-2 and MMP-9 are induced at the early stages of the hypertension, and this is probably favorable for alleviation of the initial vascular tensile stress." (PMID 27490532, 2016).